WAPL (WAPL cohesin release factor)
Description:
Regulator of sister chromatid cohesion in mitosis which negatively regulates cohesin association with chromatin. Involved in both sister chromatid cohesion during interphase and sister-chromatid resolution during early stages of mitosis. Couples DNA replication to sister chromatid cohesion. Cohesion ensures that chromosome partitioning is accurate in both meiotic and mitotic cells and plays an important role in DNA repair.
Synonyms: FOE; KIAA0261; WAPAL
Tractability: PROTAC: ubiquitination databases record sites on it; its protein half-life has been measured.
Gene: Protein-coding gene on chromosome 10 (86,435,256 to 86,521,843, reverse strand). Ensembl gene ENSG00000062650.
Subcellular location: Nucleus (Isoform 2); Nucleus; Chromosome; Cytoplasm
Subcellular location (Human Protein Atlas): Nucleoplasm
Pathways (Reactome):
Cell Cycle: Cohesin Loading onto Chromatin; Establishment of Sister Chromatid Cohesion; Resolution of Sister Chromatid Cohesion; Separation of Sister Chromatids
Gene Ontology:
Molecular function: ATP-dependent protein-DNA unloader activity; protein binding
Biological process: mitotic sister chromatid segregation; negative regulation of chromatin binding; negative regulation of DNA replication; negative regulation of sister chromatid cohesion; protein localization to chromatin; chromosome organization; mitotic cell cycle; nuclear chromosome segregation; nuclear division; regulation of cell cycle process; regulation of chromosome organization
Cellular component: chromatin; chromosome; cytoplasm; nucleoplasm; nucleus; chromosome, centromeric region; cytosol; germinal vesicle; kinetochore; nuclear lumen; synaptonemal complex
Genetic constraint (gnomAD): Loss-of-function variants: 4 observed, 110.61 expected, observed/expected ratio (o/e) 0.0362, 90% interval 0.017 to 0.083. The upper end of that interval is the gene's LOEUF score, 0.083, which puts it in group 1 of 6, group 1 being the genes least tolerant of losing a copy. Missense variants: 984 observed, 1,427.4 expected, observed/expected ratio (o/e) 0.69, 90% interval 0.65 to 0.73. Synonymous variants: 460 observed, 488.81 expected, observed/expected ratio (o/e) 0.94, 90% interval 0.87 to 1.02.
Homologues: Orthologues: chimpanzee WAPL (99% identical), macaque WAPL (99% identical), dog WAPL (96% identical), pig WAPL (95% identical), rabbit WAPL (95% identical), mouse Wapl (94% identical), rat Wapl (94% identical), guinea pig WAPL (90% identical), tropical clawed frog wapl (67% identical), zebrafish waplb (58% identical), zebrafish wapla (57% identical), Drosophila melanogaster wapl (27% identical), and 1 more.
Diseases named in the same sentence as WAPL in open-access papers:
WAPL is named in the same sentence as 18 diseases in open-access papers, as found by Europe PMC text mining. Sharing a sentence is not in itself a finding about the gene and the disease. The quoted sentences say what the papers report.
cervical cancer (3 papers, 2012 to 2024). A primary or metastatic malignant neoplasm involving the cervix. "WAPL has been associated with several cancers such as cervical cancer and esophageal carcinoma." (PMID 39480826, 2024). "We also found that KD of WAPL in human cervical cancer cells reduced estrogen sensitivity and expression of ESR1 downstream genes, MYC and Cyclin D1." (PMID 33947962, 2021). "We have previously reported that WAPL is induced by HPV E6/E7, is activated in patients with CIN and advanced cervical cancer and causes chromatin instability." (PMID 33947962, 2021). "Previously, we have isolated human wings apart-like (WAPL), which is expected to cause chromosomal instability in the process of HPV-infected precancerous lesions to cervical cancer." (PMID 33947962, 2021). "Its importance in maintaining the viability of tumor cells was demonstrated by the fact that knockdown of WAPL in cervical cancer cell lines resulted in cell death." (PMID 22412391, 2012). "Therefore, we concluded that WAPL not only induces chromosomal instability in cervical cancer tumorigenesis, but also plays a key role in activating estrogen receptor signaling in early tumorigenesis." (PMID 33947962, 2021). "We have previously reported that HPV E6/E7 increases wings apart-like (WAPL) expression, and WAPL activation in the lesions of CIN and advanced cervical cancer is involved in tumorigenesis and tumor progression." (PMID 33947962, 2021). "However, the mechanism by which activated WAPL progresses CIN and cervical cancer is not fully understood at in vivo level." (PMID 33947962, 2021). "Thus, we have uncovered a part of the roles of WAPL in the development of CIN and cervical cancer." (PMID 33947962, 2021). "However, it is still unknown whether WAPL plays a direct role in the induction of CIN, which is an early lesion of cervical cancer." (PMID 33947962, 2021).
Cornelia de Lange syndrome (2 papers, 2020 to 2022). A rare syndrome characterized by low birth weight, delayed growth, intellectual disabillity, behavioral problems, and a distinctive facial appearance (thin, arched eyebrows, low set ears, small teeth, and small nose). "NIPBL loads cohesin onto chromosomes, and WAPL takes it off.Haploinsufficiency for NIPBL causes a developmental disorder,Cornelia de Lange syndrome (CdLS), that is modeled byNipbl+/− mice." (PMID 36449618, 2022). "Variants in genes encoding various structural or functional components of the cohesin complex, including RAD21, SMC1A, SMC3, BRD4, STAG1/2, NIPBL, HDAC8, WAPL, ANKRD11 and in single individuals PDS5A and ESPL1, have been implicated in Cornelia de Lange Syndrome (CdLS)." (PMID 32193685, 2020).
acute myeloid leukemia (1 paper, 2022). Acute myeloid leukemia (AML) is a group of neoplasms arising from precursor cells committed to the myeloid cell-line differentiation. "For example, somatic mutations in the eight genes that comprise the cohesin ring (SMC1A, SMC3, STAG1, STAG2, RAD21) and the cohesin-ring support genes (NIPBL, MAU2, WAPL, PDS5A, PDS5B) and CTCF are frequently found in many cancer types and are especially common in acute myeloid leukemia (AML)." (PMID 36171609, 2022).
breast carcinoma (1 paper, 2021). "It is also reported that nPD-L1 competes with WAPL for binding to PDS5B, and regulates breast cancer cell sister chromatid cohesion." (PMID 33139930, 2021).
cervical (1 paper, 2021). "On the other hand, our previous data have suggested that HPV E6/E7 induce WAPL expression, and overexpression of WAPL in CIN is involved in cervical tumorigenesis and tumor progression." (PMID 33947962, 2021).
cervical adenocarcinoma (1 paper, 2021). An adenocarcinoma arising from the cervical epithelium. "Therefore, to investigate the correlation between MACROD1 and WAPL, we examined the effects of WAPL KD on MACROD1 in a human cervical SCC cell line SiHa and a human cervical adenocarcinoma cell line HeLa." (PMID 33947962, 2021).
chronic myeloid leukemia (1 paper, 2021). "We carried out HLM calculation for a 1.28-Mb genomic region on chromosome 8, which contains 13 CTCF-binding sites, for both wild-type (WT) and WAPL-deficient (ΔWAPL) human chronic myeloid leukemia (HAP1) cells, whose triplet contacts were measured with MC-4C." (PMID 34871311, 2021).
Lynch syndrome (1 paper, 2024). An autosomal dominant hereditary neoplastic syndrome characterized by the development of colorectal carcinoma and a high risk of developing endometrial carcinoma, gastric carcinoma, ovarian carcinoma, renal pelvis carcinoma, and small intestinal carcinoma. "The gene ontologies for list 7- linked CHTOP, ADNP, HLTF, WAPL, ZMYM4, and ZNF146 to Lynch Syndrome." (PMID 39480826, 2024). "We propose that ADNP, CHTOP, HLTF, MTF2, WAPL, and ZMYM4 are novel genes in Lynch Syndrome." (PMID 39480826, 2024).
type 2 diabetes (1 paper, 2024). "PAX5, functioning as a classical transcription factor, can regulate the expression of many genes, such as MYC, WAPL, and several type 2 diabetes-related genes, including SFRP1 and SYT12." (PMID 38926764, 2024).
cancer (9 papers, 2012 to 2025). A tumor composed of atypical neoplastic, often pleomorphic cells that invade other tissues. "Additionally, Menin-associated proteins such as WAPL play a role in maintaining sufficient cellular energy metabolism to maintain cancer growth." (PMID 39480826, 2024). "Based on these findings, we propose a working model that in cancer cells with normal Sororin expression, Sororin antagonizes WAPL and controls proper sister chromatid cohesion." (PMID 32350394, 2020). "The requirement for RAD61 in the cohesin mutants is particularly interesting given the correlation of elevated expression of the human RAD61 ortholog, WAPL, with certain cancers." (PMID 22412391, 2012). "In support of this model, elevated expression of almost every cohesin subunit (RAD21, SMC1A, SMC3, STAG1, PDS5, WAPL) and cohesin regulator (NIPBL, MAU2) appears to be oncogenic and present in a wide range of cancer cells." (PMID 41370327, 2025). "WAPL KO did not significantly alter MUTU I or GM12878 proliferation, even though it dramatically altered nuclear morphology, consistent with prior studies in EBV-negative cancer cells." (PMID 39241017, 2024).
tumor (7 papers, 2012 to 2023). "Taken together, these data indicate that the presence of tumor-derived STAG2 mutations results in a decrease in levels of cohesin and a reduction in ability of WAPL, PDS5A, and PDS5B to interact with cohesin." (PMID 26871722, 2016). "Interestingly, one group reported that PD-L1 competes with WAPL to bind to PDS5B and performs tumor progression independent of its role in the immune checkpoint." (PMID 34226509, 2021).
WAPL also shares sentences with these, for which no sentence is quoted: esophageal carcinoma (1 paper); Ewing sarcoma (1); melanoma (1); myeloid malignancies (1); pulmonary fibrosis (1); scleroderma (1); systemic lupus erythematosus (1).